GUF1 (GTP binding elongation factor GUF1)
Description:
Promotes mitochondrial protein synthesis. May act as a fidelity factor of the translation reaction, by catalyzing a one-codon backward translocation of tRNAs on improperly translocated ribosomes. Binds to mitochondrial ribosomes in a GTP-dependent manner.
Synonyms: EF-4; FLJ13220; DEE40; EF4; EIEE40
Tractability: Antibody: UniProt places it where antibodies can reach, with medium confidence. PROTAC: ubiquitination databases record sites on it; its protein half-life has been measured.
Gene: Protein-coding gene on chromosome 4 (44,678,420 to 44,700,928, forward strand). Ensembl gene ENSG00000151806.
Subcellular location: Mitochondrion inner membrane
Subcellular location (Human Protein Atlas): Mitochondria; Nucleoplasm
Gene Ontology:
Molecular function: mitochondrial ribosome binding; GTP binding; GTPase activity; ribosome binding
Biological process: positive regulation of translation; translation
Cellular component: mitochondrion; mitochondrial inner membrane; mitochondrial matrix
Genetic constraint (gnomAD): Loss-of-function variants: 33 observed, 28.7 expected, observed/expected ratio (o/e) 1.15, 90% interval 0.87 to 1.54. The upper end of that interval is the gene's LOEUF score, 1.54, which puts it in group 6 of 6, group 1 being the genes least tolerant of losing a copy. Missense variants: 364 observed, 359.28 expected, observed/expected ratio (o/e) 1.01, 90% interval 0.93 to 1.11. Synonymous variants: 144 observed, 137.69 expected, observed/expected ratio (o/e) 1.05, 90% interval 0.91 to 1.2.
Homologues: Orthologues: chimpanzee GUF1 (99% identical), macaque GUF1 (97% identical), pig GUF1 (91% identical), dog GUF1 (90% identical), rabbit GUF1 (90% identical), mouse Guf1 (87% identical), guinea pig GUF1 (87% identical), rat Guf1 (87% identical), tropical clawed frog guf1 (76% identical), zebrafish guf1 (73% identical), Drosophila melanogaster waw (51% identical), Caenorhabditis elegans ZK1236.1 (46% identical). Paralogues in human: EFL1 (25% identical), EEF2 (20% identical), GFM1 (18% identical), EFTUD2 (17% identical), GFM2 (17% identical), EEF1A1 (13% identical), EEF1A2 (13% identical), EEFSEC (12% identical), MTIF2 (12% identical), GSPT1 (11% identical), HBS1L (11% identical), TUFM (11% identical), and 6 more.
Diseases named in the same sentence as GUF1 in open-access papers:
GUF1 is named in the same sentence as 13 diseases in open-access papers, as found by Europe PMC text mining. Sharing a sentence is not in itself a finding about the gene and the disease. The quoted sentences say what the papers report.
Azoospermia (1 paper, 2024). Absence of any measurable level of sperm,whereby spermatozoa cannot be observed even after centrifugation of the semen pellet. "The remaining annotations covered polymorphic pseudogenes either linked to a provisional phenotype (e.g. GUF1), or multifactorial diseases (e.g. CYP3A5), or with late onset diseases such as macular degeneration (e.g. ARMS2), retinitis pigmentosa and azoospermia or oligospermia, OR2W3." (PMID 39488654, 2024).
endometrial cancer (1 paper, 2021). Primary or metastatic malignant neoplasm involving the endometrium (mucous membrane that lines the endometrial cavity). "For example, PAX8 and GUF1 were reported as prognostic markers for endometrial cancer, renal cancer and thyroid cancer, respectively." (PMID 34108011, 2021).
GUF1 also shares sentences with these, for which no sentence is quoted: tumor (2 papers); Arrhythmia (1); Blindness (1); cone dystrophy (1); epilepsy (1); infantile epileptic encephalopathy (1); macular degeneration (1); oligospermia (1); renal carcinoma (1); retinitis pigmentosa (1); thyroid cancer (1).